MDM2 (MDM2 proto-oncogene)
Diseases named in the same sentence as MDM2 in open-access papers (continued):
Sharing a sentence is not in itself a finding about the gene and the disease.
prostate carcinoma (continued). "Consistent with previous studies, we observed that the endogenously expressed NFAT1 protein from the nucleus of prostate cancer cells directly bound to MDM2 DNA and activated MDM2 expression, as evidenced by both EMSA and ChIP assays." (PMID 29311926, 2017). "Both MDM2 and MDMX are inappropriately upregulated and highly associated with an increased incidence of prostate cancer." (PMID 29311926, 2017). "In this population‐based case–control study, we examined the potential association between MDM4 SNP34091, alone and in combination with the MDM2 SNP309T>G (rs2279744), and the risk of breast‐, colon‐, lung‐, and prostate cancer in Norway." (PMID 26471763, 2015). "The MDM2 oncogene is amplified and/or overexpressed in many human cancers, including prostate cancer." (PMID 26041888, 2015). "PAK6 has been reported to be an important tumor suppressor in prostate cancer cells based on its ability to phosphorylate the androgen receptor, tumorigenic E3 ligase murine double minute-2 (Mdm2), and β-catenin." (PMID 25714010, 2015). "The present study also shows that WZ35 treatment inhibited G2/M progression in prostate cancer cells, in association with the decreased expression of CDC2, cyclinB1, and MDM2." (PMID 26546056, 2015). "Pharmacologic activation of AMPK suppresses EMT by modulating the Akt-MDM2-Foxo3 signaling axis in breast and prostate cancer cells." (PMID 25871400, 2015). "We show here that 280B up-regulates expression of Mdm2 in prostate cancer cells, and this regulation is via the Mdm2 promoter." (PMID 24236047, 2013). "Conversely, treatment of prostate cancer cells with an inhibitor of miR-125b (anti-miR-125b) resulted in increased expression of p14ARF, decreased level of Mdm2, and induction of apoptosis." (PMID 23585871, 2013). "Combining MDM2 overexpression and high Ki-67 resulted in increased prognostic significance for distant metastasis (p < 0.0001), prostate cancer death (p < 0.0001) and overall survival (p = 0.0002)." (PMID 22292443, 2012). "MDM2 individually and particularly in combination with Ki-67 appears to be a robust molecular biomarker for prostate cancer patients treated with radiation therapy." (PMID 22292443, 2012). "Only a limited number of studies had examined MDM2 as a biomarker in prostate cancer specimens with mostly uncontrolled cohorts." (PMID 22292443, 2012).
prostate carcinoma (continued). "Thus, our study expands the known roles of MDM2 in prostate cancer to include its potential involvement in the important mutual stabilization that TM4SF3 exhibits when interacting with either AR or AR-V7." (PMID 38410785, 2024). "VNPP433-3β inhibits nuclear translocation of f-AR and f-AR-mediated oncogenic transcription by chemically inducing proximity of f-AR and E3 ligase MDM2 triggering targeted degradation of f-AR rapidly thereby inhibiting development and progression of prostate cancer." (PMID 36831540, 2023). "Anti-androgens induce FBW7 and MDM2 transcripts and promote the degradation of a target ion channel KCa1.1; ARs will likely also be subject to ubiquitin-mediated degradation as it is a target for the Ub-E3 activity of MDM2 in prostate cancer." (PMID 38203649, 2023). "A recent study provided evidence that MDM2 is an important regulator of prostate cancer stem cells." (PMID 31366128, 2019). "Global MDM2 overexpression does not correlate with disease outcome; however, high-MDM2 score was associated with distant metastasis and mortality in patients treated with radiotherapy and androgen deprivation for prostate cancer." (PMID 31366128, 2019). "In the present study, we have used the human angiogenesis RT2 profiler PCR array to compare the gene expression profile between LNCaP and LNCaP-MST (MDM2 transfected) prostate cancer cells, along with LNCaP-MST cells treated with Nutlin-3, an MDM2 specific inhibitor." (PMID 29748481, 2018). "Furthermore, co-expression of MDM2 and MDMX increased levels of co-transfected AR-GFP, a hybrid gene under the CMV promoter, indicating that MDM2/MDMX co-expression increases the stability of AR in prostate cancer cells." (PMID 29464071, 2018). "The MDM2 and MDMX oncogenes are overexpressed in various types of human cancer and are highly associated with the initiation, progression, metastasis and chemotherapeutic resistance of these diseases, including prostate cancer." (PMID 29311926, 2017). "This may be clinically relevant, given that prostate cancers only rarely harbor MDM2 amplifications." (PMID 27729622, 2016). "Finally, we demonstrate that the unrelated MDM2 antagonist Mi-63 also impinges upon AR signalling, supporting the concept of future treatment of prostate cancer with MDM2 antagonists." (PMID 27729622, 2016). "We have recently identified a novel ginsenoside, 25-OCH3-PPD (GS25), one of the most active anticancer ginsenosides discovered thus far, and have demonstrated its MDM2 inhibition and anticancer activity in various human cancer models, including prostate cancer." (PMID 26041888, 2015).
prostate carcinoma (continued). "After GS25 was successfully encapsulated into PEG-PLGA nanoparticles (GS25NP) and its physicochemical properties were characterized, the efficiency of MDM2 targeting, anticancer efficacy, pharmacokinetics, and safety were evaluated in in vitro and in vivo models of human prostate cancer." (PMID 26041888, 2015). "Note that Mdm2 is primarily cytoplasmic in prostate cancer cells." (PMID 24236047, 2013). "Thus, it was unsurprising that MDM2 affected gene expression in prostate cancer cells." (PMID 38410785, 2024). "Thus, Luteolin was found to regulate E-cadherin through the Akt/MDM2 pathway in prostate cancer." (PMID 36992138, 2023). "Interestingly, MDM2 level is up-regulated in nearly one-third of prostate cancers." (PMID 29748481, 2018). "Therefore, the dual inhibitory effects of InuA on the MDM2–MDMX interaction and the NFAT1–MDM2 interaction may translate into enhanced anti-prostate cancer activity." (PMID 29311926, 2017). "This phosphorylation of AR may lead to Mdm2-mediated protein degradation in prostate cancer cells." (PMID 26318424, 2015). "The results of previous studies and of the present study indicate that the inhibition of Akt activation by luteolin may result in the downregulation of Mdm-2 and cyclin D1, which may contribute to the induction of apoptosis and cell cycle arrest in colon and prostate cancer cells." (PMID 22269172, 2012).
prostate carcinoma (continued). "We now show that Mdm2 C305F mutation results in decreased prostate size and, unlike the situation in Myc-induced B cell lymphomagenesis, slows the progression of prostate tumorigenesis induced by inactivation of pRb family proteins in the well-characterized APT121 mouse model of prostate cancer." (PMID 21747916, 2011). "In prostate cancer cells PC3, suppression of mdm2 levels, induction of E‐cadherin, and prevention from invasion were noted to be associated with luteolin administration." (PMID 39830909, 2025). "This study identifies MDM2 as a potential common E3 ligase for AR, AR-V7, and TM4SF3 in prostate cancer cells and suggests a novel mechanism for the mutual stabilization of TM4SF3 with AR or AR-V7 by disrupting the action of MDM2 on these proteins." (PMID 38410785, 2024). "Collectively, these data strongly suggest that MDM2 E3 ligase activity diminishes the protein levels of both AR and TM4SF3 in prostate cancer cells." (PMID 38410785, 2024). "In this study, we found that inhibiting MDM2, either by siRNA or a pharmacological inhibitor of its RING domain, increased levels of AR, AR-V7, and TM4SF3 protein in prostate cancer cells, leading to elevated growth of these cells." (PMID 38410785, 2024). "For instance, following treatment with Inulanolide A, a drug that hampers the binding of MDM2-MDMX, reduced proliferative and invasive potentials were observed in prostate cancer." (PMID 37314603, 2023). "MDM2 and c-terminus of HSP70-interacting protein (CHIP)-mediated ubiquitination induces AR degradation in prostate cancer." (PMID 31896509, 2020). "In various cancers, including prostate cancer and ovarian carcinoma, upregulation of USP2 leads to an increase in the levels of deubiquitinated substrates such as fatty acid synthase, MDM2, cyclin D1 and Aurora-A." (PMID 29449607, 2018).
prostate carcinoma (continued). "The murine double minute (MDM) oncogene family, consisting of MDM2 and MDMX, has been demonstrated to be a promising molecular target for the prevention and treatment of various types of human cancer, including prostate cancer." (PMID 29311926, 2017). "Because InuA exhibited a concentration-dependent inhibition of NFAT1 in prostate cancer cells, we examined the role of NFAT1 in InuA’s anti-MDM2 and anticancer activities." (PMID 29311926, 2017). "Next, we examined the effects of InuA on the protein expression of MDM2 and MDMX in prostate cancer cells." (PMID 29311926, 2017). "InuA decreased the protein expression levels of both MDM2 and MDMX in a concentration-dependent manner in all three prostate cancer cell lines." (PMID 29311926, 2017). "In summary, we have prepared and characterized an oral nano-delivery system for a novel natural MDM2 inhibitor, GS25, and herein demonstrated its pharmacokinetics, efficacy, and safety in various preclinical models of human prostate cancer." (PMID 26041888, 2015). "More recently, these bacteria have been engineered to express numerous genes, including survivin, MDM2, Neu3 and STAT3 siRNA against prostate cancer in our laboratory." (PMID 23721095, 2013). "In prostate cancer, PC3 cells treated with luteolin showed poor cellular adhesion as well as increase in cell invasion through the AKT pathway via increasing E‐cadherin expression by inhibiting mouse double minute 2 (mdm2) gene." (PMID 39830909, 2025). "This indicates that the involvement of FOXO1 in MDM2 expression may be cell type–dependent and that transcription factors other than FOXO1 may regulate MDM2 expression in prostate cancer cells." (PMID 38519029, 2024). "MDM2 inhibition by siRNA depletion or using a pharmacological inhibitor (MDM2i) of its E3 ligase activity led to elevated levels of endogenous AR, AR-V7, and TM4SF3 in prostate cancer cells." (PMID 38410785, 2024). "In prostate cancer, FOXQ1 regulated the expression of BCL11A/MDM2 to promote cell proliferation." (PMID 33748185, 2021). "Together, our results indicate that combinatorial inhibition of MDM2 and MDMX may offer a novel compelling strategy for prostate cancer therapy." (PMID 29464071, 2018). "Since the roles of MDM2 and its analog MDMX in cancer metastasis continue to evolve, we have conducted several studies on the levels of differentially expressed genes using LNCaP and LNCaP-MST prostate cancer cells." (PMID 29748481, 2018). "Novel approaches for inhibiting the MDM oncoproteins, MDM2 and MDMX, are worthy of investigation and might be used clinically for the prevention and treatment of human prostate cancer, especially CRPC." (PMID 29311926, 2017). "Double knockdown of MDM2 and NFAT1 also revealed that the expression of both of these molecules is important for InuA’s inhibitory effects on the proliferation and invasion of prostate cancer cells." (PMID 29311926, 2017). "Finally, we found that the inhibitory effects of InuA on MDM2 and NFAT1 were critical for its anti-prostate cancer activities, as demonstrated using MDM2 and NFAT1 double KD prostate cancer cell lines." (PMID 29311926, 2017).